HILPDA (hypoxia inducible lipid droplet associated)
Diseases named in the same sentence as HILPDA in open-access papers (continued):
Sharing a sentence is not in itself a finding about the gene and the disease.
tumor (30 papers, 2005 to 2025). "Hypoxia-inducible lipid droplet-associated (HILPDA) was overexpressed in multiple tumor types, HILPDA was positively correlated with tumor-associated macrophages (TAM) infiltration, and immunosuppressive genes, such as PD-L1, PD-1, TGFB1, and TGFBR1." (PMID 36439512, 2022). "Hypoxia-inducible lipid droplet associated protein (HILPDA) plays an oncogenic role in various tumor types." (PMID 33816230, 2021). "The difference in HILPDA expression levels in different tumor types may reflect the distinct underlying functions and mechanisms." (PMID 33816230, 2021). "This evidence positions HILPDA as a molecular mediator bridging immune-stromal crosstalk, actively reprogramming the tumor microenvironment through lipid metabolic remodeling." (PMID 40861438, 2025). "We further validated in vitro that the KynA/P4HA2/HILPDA axis mediates lipid metabolism reprogramming in tumor cells." (PMID 39920992, 2025). "Peri-necrotic and palisading tumor regions also exhibited elevated expression of hypoxia-response genes such as HILPDA, LDHA, ENO2, and DDIT3 relative to other regions." (PMID 35973991, 2022). "We found the positive correlation between HILPDA expression and immunosuppressive genes, such as PD-L1, PD-1, TGFB1, and TGFBR1, indicates the key role of HILPDA in regulating tumor immunosuppressive microenvironment." (PMID 33816230, 2021). "Correlation analysis revealed that HILPDA expression was positively correlated with infiltration levels of macrophages in most tumor types, including BRCA, CESC, LIHC, PAAD, PCPG, SKCM, STAD, and UCS." (PMID 33816230, 2021). "As the high infiltration of TAMs in tumor often indicates the immunosuppressive microenvironment, we further investigated the relationship between HILPDA expression and tumor immunosuppressive microenvironment." (PMID 33816230, 2021). "In this study, we evaluated HILPDA expression in different tumor types from The Cancer Genome Atlas (TCGA) database and its association with tumor stage and prognosis of patients." (PMID 33816230, 2021). "SPP1, CRYAB, NNMT and HILPDA were highly expressed in tumour cells (ccRCC1); GSTA2, BHMT and ADSSL1 were highly expressed in tumour cells 1 (ccRCC2); and HIF1A-AS2, DNAH11 and EGOT were highly differentially expressed in tumour cells 2 (ccRCC2)." (PMID 34168986, 2021). "FADS2 and HILPDA showed significantly elevated levels in tumor cells." (PMID 40977891, 2025). "Notably, HIF-1α has been shown to bind to the promoter region of the HILPDA gene to activate transcription of HILPDA, as well as promote tumor proliferation, metastasis, and drug resistance." (PMID 39920992, 2025). "Notably, we found that cells in cluster four shows an increased expression of genes related to the hypoxia (e.g., HILPDA), tumor angiogenesis (e.g., VEGF and NRN1) and glycolytic (e.g., ENO2)." (PMID 34805184, 2021). "Additionally, high HILPDA expression was associated with worse overall survival (OS), disease-specific survival (DSS), and progression-free intervals (PFI) in most tumor types." (PMID 33816230, 2021). "HILPDA was predicted to participate in pathways related to the cell cycle and tumor immunity." (PMID 33816230, 2021). "Moreover, HILPDA expression was positively correlated with TAM infiltration level in most tumor types." (PMID 33816230, 2021). "HILPDA is involved in the progression of many diseases, including several tumor types." (PMID 33816230, 2021). "Therefore, it is urgent to clarify the role of HILPDA in tumor progress and treatment." (PMID 33816230, 2021). "Finally, analysis of lipid storage markers showed an increased expression of perilipin 2 (PLIN2) and hypoxia inducible lipid droplet-associated (HILPDA), and reduced levels of carnitine palmitoyltransferase 1A (CPT1A) mRNA in tumor specimens compared to normal kidney." (PMID 33322148, 2020). "Therefore, we hypothesize that mir-150 could be acting through lymphocyte-derived EVs to downregulate HILPDA expression in tumor cells." (PMID 32024530, 2020).
tumor (continued). "Using three spatially-enriched marker genes for each tumor subregion (CT: BCAN, CSPG5, TOP2A; Pseudo: HILPDA, IGFBP5, LGALS3; and MVP: MGP, LUM, THBS1) we identified distinct sub-populations of malignant cells from the scRNA-seq data." (PMID 41366031, 2025). "Previous studies have shown that HILPDA is regulated by HIF-1α and that HIF-1α functions as a transcription factor in tumor progression." (PMID 39920992, 2025). "Our results offer novel insights into the functional role of HILPDA and further highlight a potential mechanistic basis whereby HILPDA influences TAM infiltration and immunosuppressive gene expression in the tumor microenvironment." (PMID 33816230, 2021). "However, the roles of HILPDA in most tumor types remain unclear." (PMID 33816230, 2021). "Our results offer novel insights into the functional role of HILPDA and further highlight a potential mechanistic basis whereby HILPDA influences TAM infiltration and immunosuppressive gene expression in tumor microenvironment." (PMID 33816230, 2021). "HILPDA is a direct target of HIF-1α and PPARα, and elevated expression in hypoxia increases the number of lipid droplets in tumor cells." (PMID 27765905, 2016). "Tumor-cell-specific deMuts included many COSMIC genes, such as VEGFA, NEAT1, MALAT1, HILPDA, etc.." (PMID 37433798, 2023).
infection (4 papers, 2018 to 2023). The state of being infected such as from the introduction of a foreign agent such as serum, vaccine, antigenic substance or organism. "Our results identified the infection-mediated upregulation of genes encoding lipid droplet-associated molecules, including anti-lipolytic HCAR2, perilipin -2 and -3, which regulate lipid droplet formation and degradation and HILPDA." (PMID 35531332, 2022).
HILPDA also shares sentences with these, for which no sentence is quoted: atherosclerosis (2 papers); colorectal cancer (2); glioblastoma (2); lymphoma (2); neuroblastoma (2); schizophrenia (2); Alzheimer disease (1); anaplastic astrocytoma (1); astrocytomas (1); autoimmune disease (1); colorectal adenoma (1); head and neck carcinoma (1); head and neck squamous cell carcinoma (1); kidney cancer (1); kidney tumours (1); leukaemias (1); liver steatosis (1); lung squamous cell carcinoma (1); Lyme disease (1); metastatic melanoma (1); ovarian carcinoma (1); ovarian clear cell cancer (1); Parkinson disease (1); Raine syndrome (1); rectum adenocarcinoma (1); steatosis (1); stomach tumours (1); uterine corpus endometrial carcinoma (1).